ZSCAN2 (zinc finger and SCAN domain containing 2)
Description:
May be involved in transcriptional regulation during the post-meiotic stages of spermatogenesis.
Synonyms: ZFP29; ZNF854; FLJ20595
Tractability: PROTAC: ubiquitination databases record sites on it.
Gene: Protein-coding gene on chromosome 15 (84,600,986 to 84,627,796, forward strand). Ensembl gene ENSG00000176371.
Subcellular location: Nucleus
Subcellular location (Human Protein Atlas): Nucleoplasm; Cytosol
Gene Ontology:
Molecular function: DNA-binding transcription factor activity, RNA polymerase II-specific; RNA polymerase II transcription regulatory region sequence-specific DNA binding; sequence-specific double-stranded DNA binding
Biological process: regulation of transcription by RNA polymerase II
Cellular component: nucleus
Genetic constraint (gnomAD): Loss-of-function variants: 28 observed, 51.97 expected, observed/expected ratio (o/e) 0.54, 90% interval 0.4 to 0.74. The upper end of that interval is the gene's LOEUF score, 0.74, which puts it in group 3 of 6, group 1 being the genes least tolerant of losing a copy. Missense variants: 730 observed, 825.64 expected, observed/expected ratio (o/e) 0.88, 90% interval 0.83 to 0.94. Synonymous variants: 305 observed, 304.49 expected, observed/expected ratio (o/e) 1, 90% interval 0.91 to 1.1.
Homologues: Orthologues: chimpanzee ZSCAN2 (99% identical), macaque ZSCAN2 (97% identical), dog ZSCAN2 (90% identical), rat Zscan2 (90% identical), mouse Zscan2 (89% identical), guinea pig ZSCAN2 (83% identical), rabbit ZSCAN2 (82% identical). Paralogues in human: ZSCAN20 (48% identical), ZNF256 (36% identical), ZNF304 (36% identical), ZNF551 (35% identical), ZNF583 (35% identical), ZNF79 (35% identical), ZNF792 (35% identical), ZNF480 (34% identical), ZNF587B (34% identical), ZNF570 (33% identical), ZNF418 (32% identical), ZNF549 (32% identical), and 26 more.
Diseases named in the same sentence as ZSCAN2 in open-access papers:
ZSCAN2 is named in the same sentence as 8 diseases in open-access papers, as found by Europe PMC text mining. Sharing a sentence is not in itself a finding about the gene and the disease.
ZSCAN2 shares sentences with these, for which no sentence is quoted: schizophrenia (2 papers); attention deficit-hyperactivity disorder (1); autism spectrum disorder (1); bipolar disorder (1); cancer (1); generalized anxiety disorder (1); obsessive-compulsive disorder (1); unipolar depression (1).